SNORD115-30 (small nucleolar RNA, C/D box 115-30)
Synonyms: HBII-52-30
Gene: Small nucleolar RNA gene on chromosome 15 (25,225,203 to 25,225,284, forward strand). Ensembl gene ENSG00000200987.
Gene Ontology:
Biological process: RNA processing
Cellular component: nucleolus
Homologues: Orthologues: chimpanzee SNORD115 (96% identical), macaque SNORD115 (95% identical). Paralogues in human: SNORD115-6 (98% identical), SNORD115-11 (96% identical), SNORD115-29 (96% identical), SNORD115-34 (96% identical), SNORD115-36 (96% identical), SNORD115-42 (96% identical), SNORD115-43 (96% identical), SNORD115-12 (95% identical), SNORD115-15 (95% identical), SNORD115-16 (95% identical), SNORD115-22 (95% identical), SNORD115-26 (95% identical), and 37 more.